MMP9 (matrix metallopeptidase 9)
Diseases named in the same sentence as MMP9 in open-access papers (continued):
Sharing a sentence is not in itself a finding about the gene and the disease.
oral squamous cell carcinoma (continued). "Our method reached a MMP-9 detection limit of 75 ng·mL−1, which is low enough for diagnostics applications like the differential diagnosis of oral squamous cell carcinoma (OSCC), for which the excellent performance observed in saliva samples is highly promising." (PMID 37303001, 2023). "CircMMP9 could interact with both AUF1 and miR-149, and block the inhibitory effect of AUF1 and miR-149 on the 3’-UTR of MMP9 to enhance the stability of MMP9 mRNA, thereby promoting the metastasis of oral squamous cell carcinoma." (PMID 37060016, 2023). "Furthermore, the pro-MMP-9 is subsequently cleaved into its mature active form MMP-9 by gingipains and promotes the invasion of oral squamous cell carcinoma." (PMID 34588004, 2021). "Moreover, MMP-2 and MMP-9 are overexpressed in the biopsy specimens of oral squamous cell carcinoma compared to the adjacent normal tissues." (PMID 32429564, 2020). "In oral squamous cell carcinoma (OSCC), the activation level of MMP-9 may be associated with a shortened disease-free survival and a high metastatic frequency." (PMID 23365550, 2013). "Furthermore, MMP-9 is a predictor of tumor recurrence in oral squamous cell carcinoma." (PMID 36674806, 2023). "Moreover, curcumin-mediated inhibition of Notch-1 activation also led to the downregulation of NF-κB and its target genes, including Bcl-2, cyclin D1, vascular endothelial growth factor (VEGF), and matrix metalloproteinase -9 (MMP-9) in oral squamous cell carcinoma cells." (PMID 22363450, 2012). "Gal-7 can stimulate the expression of MMP-9 and MMP-2, facilitating the progression and metastasis of oral squamous cell carcinoma (OSCC)." (PMID 40134029, 2025). "Dias and colleagues found that reducing metallothionein 2A levels using siRNA lowered MMP-9 and EGF protein levels, leading to decreased proliferation, migration, and invasion in human oral squamous cell carcinoma cells." (PMID 38374934, 2024). "In oral squamous cell carcinoma (OSCC), MED1, a subunit of the Mediator complex, activates the transcription of MMP-9 while simultaneously inhibiting CD8+ T-cell antitumor immune responses." (PMID 39712025, 2024). "In oral squamous cell carcinoma, the knockdown of LCN2 correlated with increased cancer cell malignant potential and resistance against chemotherapy with upregulated MMP-9 expression." (PMID 34062746, 2021). "Another study shows that infection of Porphyromonas gingivalis increases the aggressiveness, metastasis, and viability of oral squamous cell carcinoma (OSCC) through the induction of canonical EMT markers, MMP-9 and vimentin." (PMID 34827233, 2021). "Although the overexpression of MMP-9 was detected in Oral squamous cell carcinoma (OSCC) tissues, further basic studies in vivo and in vitro are needed to investigate the role of MMP-9 in OSCCs and provide scientific validation." (PMID 32382550, 2020). "In smoke-exposed oral squamous cell carcinoma (OSCC), matrix metalloproteinase-9 (MMP-9) facilitates cell invasion by degrading extracellular matrix components like collagen, enabling cancer cells to invade surrounding tissues and metastasize, thus exacerbating disease progression." (PMID 41048327, 2025). "Our research indicates that MED1 may indirectly impact the function of CD8+ T cells within the immune microenvironment of oral squamous cell carcinoma (OSCC) through the Notch signaling pathway, in addition to its direct regulation of MMP9." (PMID 39343952, 2024). "In tongue squamous cell carcinoma, MMP9 expression is elevated in neoplastic cells along the infiltration front, and MMP9 expression in histologically negative surgical margins of oral squamous cell carcinoma (OSCC) is a predictor of tumor recurrence." (PMID 36059672, 2022).
oral squamous cell carcinoma (continued). "In oral squamous cell carcinoma, FABP5 regulates MMP-9 expression and tumor invasion." (PMID 34685761, 2021). "Lastly, in oral squamous cell carcinoma (OSCC) cells, P. gingivalis promotes cellular migration through activation of the ERK1/2-Ets1, p38/HSP27, and PAR2/NF-κB pathways to induce pro-matrix metalloproteinase (MMP)-9 expression." (PMID 26788120, 2016). "Additionally, scutellarin may control the level of the transcription factor AP-1 to inhibit tumor angiogenesis in oral squamous cell carcinoma(OSCC), which is accomplished by decreasing the MMP-9 and MMP-2 levels, alongside decreasing integrin αvβ6 levels regarding human tongue cancer SAS cells." (PMID 38611849, 2024).
chronic obstructive pulmonary disease (64 papers, 2007 to 2025). A chronic and progressive lung disorder characterized by the loss of elasticity of the bronchial tree and the air sacs, destruction of the air sacs wall, thickening of the bronchial wall, and mucous accumulation in the bronchial tree. "MMP9 is implicated in chronic inflammatory conditions, such as chronic obstructive pulmonary disease (COPD), where its activity could lead to structural changes in lung tissue." (PMID 41259376, 2025). "MMP9 is a commonly found biomarker associated with cardiac arrhythmias." (PMID 35742954, 2022). "Relevant literatures reporting MMP9 and susceptibility to COPD in PubMed, Web of Science, VIP, Wanfang and CNKI databases were searched using the key words "matrix metalloproteinases 9/MMP9, COPD/chronic obstructive pulmonary disease"." (PMID 36042908, 2022). "One of the members of the MMP family, MMP-9, is a gelatinase that has been implicated in the pathogenesis of atherosclerosis and chronic obstructive pulmonary disease (COPD) in addition to tumor formation and metastasis." (PMID 23825535, 2013). "A previous document proved that GPNMB can influence MMP9 expression in chronic obstructive pulmonary disease." (PMID 38924029, 2024). "SIRT1 was found to induce ECM degradation by deacetylating histones on the MMP9 promoter, thereby suppressing its transcription in chronic obstructive pulmonary disease (COPD)." (PMID 36864460, 2023). "The MMP-9/TIMP-1 imbalance is associated with multiple disorders such as autoimmune diseases, chronic obstructive pulmonary disease exacerbations and blood-brain barrier disruption." (PMID 34571700, 2021). "MMP-9 also facilitates the recruitment of inflammatory cells in the airways during allergic inflammation and chronic obstructive pulmonary disease." (PMID 27637086, 2016). "SAA1 is related to the acute exacerbation of chronic obstructive pulmonary disease, and higher levels of MMP-9 correspond to a higher influx of neutrophils and lymphocytes, signaling an exacerbation of COPD in which a higher burden of MMP-9 is observed in the airways." (PMID 40228208, 2025). "Moreover, the concentration and activity of MMP-9 correlates with the disease severity of chronic obstructive lung disease." (PMID 30766447, 2019). "In addition, macrophages form the main source of MMP-9 in normal lungs, but neutrophils secrete MMP-9 in chronic obstructive lung disease." (PMID 30766447, 2019). "Several inflammatory mediators, such as NF-kB, TNF-α, and MMP-9, were observed to be higher in chronic obstructive pulmonary disease (COPD) patients than in healthy controls and were reduced after treatment with RSV." (PMID 35056739, 2022). "The aim of this study was to evaluate serum levels of both MMP-9 and TIMP-1 in COPD patients and to assess their relationship with lung function, symptom severity scores and acute exacerbations of chronic obstructive pulmonary disease (AECOPD)." (PMID 36935521, 2023). "In chronic obstructive pulmonary disease (COPD), increased expression of MMP-9 by inflammatory cells e.g., neutrophils and macrophages, is correlated with a variety of processes that cause lung damage." (PMID 30669448, 2019). "As matrix metalloproteinases (MMPs), especially MMP-9 and MMP-12 are involved in the pathological processes associated with chronic obstructive pulmonary disease (COPD), we developed a novel radiofluorinated probe, 18F-IPFP, for MMPs-targeted positron emission tomography (PET)." (PMID 29358724, 2018). "The present study aims to investigate the effect of Liuweibuqi (LWBQ) capsules on the expression of matrix metalloproteinase (MMP)-9 and TIMP1 and cell viability of alveolar macrophages (AMs) in chronic obstructive pulmonary disease (COPD)." (PMID 28831024, 2017). "Furthermore, MMP-9 is involved in the pathogenesis of inflammatory bowel disease, rheumatoid arthritis and chronic obstructive pulmonary disease (COPD)." (PMID 23139770, 2012).
chronic obstructive pulmonary disease (continued). "In chronic obstructive pulmonary disease (COPD), the level of metalloproteinases-9 (MMP9) might increase in consequence of Sirt1 reduction." (PMID 33121118, 2020). "Chronic obstructive pulmonary disease (COPD) is “the third killer” in the worldwide public health problem characterized by progressive airflow limitation, progressive lung inflammation and increases in the levels of some inflammatory mediators such as MMP-9, TNF-α and IL-8." (PMID 30909565, 2019). "ACP was also found to overexpress MMP9 (FC = 41.0, p = 9.8 × 10−14) and, more strikingly, MMP12 (FC = 819.7, p = 3.0 × 10−49), which are both inhibited by AZD1236, a drug originally tested as a treatment for chronic obstructive pulmonary disease, but more recently investigated as an antitumor agent." (PMID 25990246, 2015).
diabetic retinopathy (64 papers, 2013 to 2025). "Activation of MMPs in diabetic retinopathy is implicated in mitochondrial damage, and inhibition of MMP-9 prevents mitochondrial damage and the development of retinopathy in diabetic mice." (PMID 37596436, 2024). "MMP-9 has a very important role in diabetic retinopathy and its increased levels are one of the main factors causing retinal capillary apoptosis." (PMID 35729613, 2022). "Zhong and Kowluru found that mitochondrial damage and dysfunction induced by histone methylation of MMP-9 cause mitochondrial ROS overproduction and thus accelerate the progression of diabetic retinopathy." (PMID 35340204, 2022). "The proinflammatory state that exists in patients with diabetic retinopathy was suggested to cause overexpression of MMP-9." (PMID 30149671, 2018). "It was also reported that quercetin in higher doses than 1 μM significantly inhibited MMP9 in a flavonoid–enzyme interaction model and in rats with diabetic retinopathy." (PMID 40566630, 2025). "Experimental models have revealed that generation of cytosolic ROS via Rac1-Nox2 signaling and the activation of MMP-9 are early events in the pathogenesis of diabetic retinopathy." (PMID 36672234, 2023). "Diabetic retinopathy can be suppressed by inhibition of MMP-9 and MMP-14 levels which indicates a new form of treatment." (PMID 35729613, 2022). "Pharmacological inhibition of MMPs in the development of diabetic retinopathy protects from retinal and choroidal neovascularization and prevents MMP-9-related vascular permeability and inflammation." (PMID 35729613, 2022). "High glucose decreases the dimethylation of H3K9 regulated by LSD1 and increases the phosphorylation of NF-κB P56 at the MMP-9 promoter, resulting in mitochondrial ROS overproduction in diabetic retinopathy." (PMID 35340204, 2022). "Next, we analyzed the expression of Matrix metallopeptidase 9 (MMP9), a well-known mediator of extracellular matrix breakdown and angiogenesis upregulated in patients with diabetic retinopathy and rodent models." (PMID 34520511, 2021). "PARP1 was shown to promote nuclear translocation of RelA (p65) in T. cruzi-infected cardiomyocytes and to enhance NF-κB/AP-1 binding to the MMP9 promoter sequence in diabetic retinopathy and JNK-dependent activation of AP-1 in murine fibroblasts." (PMID 33172999, 2020). "The activation of MMP-9, in particular, induced apoptosis in the retina capillary cells in the pathogenesis of diabetic retinopathy, showing that an elevation on MMP levels seems to be associated with the apoptosis process." (PMID 33261005, 2020). "Hyperhomocysteinemia is implicated in increased oxidative stress and activation of MMP-9, and in diabetic retinopathy, the activation of MMP-9 facilitates capillary cell apoptosis." (PMID 32150828, 2020). "PARP1 is shown to activate JNK and DNA binding of AP-1 in fibroblasts and enhance NF-κB/AP-1 binding to MMP9 promoter sequence in diabetic retinopathy, though its role in transcriptional activation of the profibrotic program in Mφ, if any, is not known." (PMID 33172999, 2020). "The aim of this study was to investigate the mechanism by which homocysteine activates MMP-9 in diabetic retinopathy." (PMID 32150828, 2020). "The way in which elevated homocysteine regulates retinal MMP-9 activation in diabetic retinopathy is unclear." (PMID 32150828, 2020). "Activation of MMP-2 and MMP-9 is important in pathogenesis of diabetic microangiopathic complications such as diabetic retinopathy, nephropathy, and neuropathy." (PMID 32093214, 2020). "Our aim was to investigate the mechanism by which homocysteine activates MMP-9 in diabetic retinopathy." (PMID 32150828, 2020). "For example, levels of MMP-2 and MMP-9 were significantly higher in the retina and vitreous of diabetic retinopathy patients and animal models." (PMID 31398819, 2019).
diabetic retinopathy (continued). "Here, MMP-9 would weaken the blood–retinal barrier, thereby breaking down endothelial tight junction protein cadherin and occluding in the early stages of diabetic retinopathy." (PMID 30149671, 2018). "A dynamic balance between methyl cytosine and hydroxyl methylation of MMP9 was found to be important in MMP9 expression and in maintaining mitochondrial integrity and function in RECs and in preventing diabetic retinopathy." (PMID 29085333, 2017). "Matrix metalloproteinase-9 (MMP-9) has an important role in the pathogenesis of diabetic retinopathy." (PMID 28183874, 2017). "For instance, the elevated level of MMP-9 in plasma and retinas of diabetic patients can contribute to the development of diabetic retinopathy by altering vascular permeability and capillary cell apoptosis." (PMID 27781209, 2016). "Vitreous MMP-9 has demonstrated a positive correlation with the severity of diabetic retinopathy, with the suggestion that MMP inhibitors may lead to better visual outcomes." (PMID 40563988, 2025). "Also, matrix metalloproteinases (MMPs), including MMP-9, are enzymes involved in the degradation of extracellular matrix proteins and probably in the disruption of the blood–retinal barrier in diabetic retinopathy." (PMID 40724509, 2025). "Moreover, LSD1 siRNA ameliorated the glucose-induced reduction in H3K9me2 reduction and increase in p65 in the MMP-9 promoter region in ophthalmological diseases and prevented MMP-9 activation, mitochondrial damage, and apoptosis in diabetic retinopathy." (PMID 39130627, 2024). "Our previous studies have shown that in the pathogenesis of diabetic retinopathy, activation of cytosolic matrix metalloproteinases (MMPs) in the retina damages the mitochondria; the effect of inhibition of MMP-9 activation on the removal of the damaged mitochondria was evaluated." (PMID 37596436, 2024). "MMP9 is thought to be mitochondria-localized and contributes to mitochondrial dysfunction, as well as the activation of mitochondrial permeability transition after cardiac damage and diabetic retinopathy." (PMID 38132094, 2023). "Thus, MMP-9, which damages the mitochondria in the early stages, assists in new vessel formation in the development of diabetic retinopathy." (PMID 36672234, 2023). "Similarly, H3K9me2 demethylation mediated by LSD1 repressed MMP-9-modulated mitochondrial ROS production in diabetic retinopathy." (PMID 35340204, 2022). "In addition, the enzyme matrix metalloproteinase-9 (MMP-9) has been linked to the initiation and progression of diabetic retinopathy." (PMID 36333816, 2022). "MMP-9 is known to degrade occludin and claudin-5 in focal cerebral ischemia, and it has been reported that it affects the expression of occludin, claudin-5, and ZO-1 and ZO-2 levels in early diabetic retinopathy." (PMID 32178308, 2020). "Whether BGP-15 may affect in this pathway beside HSP72 either SIRT1 or MMP9 and thus the pathogenesis of diabetic retinopathy was still to be discovered." (PMID 32204537, 2020). "In line with the findings, a recent study demonstrated that HMGB-1 promoted lymphangiogenesis via TLR4/NF-ΚB/MMP9 signaling pathway, indicating that HMGB-1 may play an important role in diabetic retinopathy by modulating MMP9." (PMID 27847406, 2016). "MMP-2 and MMP-9 are extracellular proteinases that have been revealed to play an important role in retinal neovascularization and increasing of vascular permeability seen in the late development of diabetic retinopathy." (PMID 25123184, 2014). "Thus, MMP-9 inhibitors may have potential preventive effects in the development of diabetic retinopathy." (PMID 38999417, 2024). "Thus, in the pathogenies of diabetic retinopathy, MMP-9 has a major role in damaging the mitochondria and accelerating the apoptotic machinery, and Ezh2 appears to be critical in maintenance of cellular epigenetic integrity by regulating both histone modifications and DNA methylation." (PMID 29261844, 2017).